DBT (dihydrolipoamide branched chain transacylase E2)
Description:
The branched-chain alpha-keto dehydrogenase complex catalyzes the overall conversion of alpha-keto acids to acyl-CoA and CO(2). It contains multiple copies of three enzymatic components: branched-chain alpha-keto acid decarboxylase (E1), lipoamide acyltransferase (E2) and lipoamide dehydrogenase (E3). Within this complex, the catalytic function of this enzyme is to accept, and to transfer to coenzyme A, acyl groups that are generated by the branched-chain alpha-keto acid decarboxylase component.
Synonyms: BCOADC-E2; BCKAD-E2; BCKADE2; BCKDH-E2; BCATE2; E2; E2B
Tractability: Small molecule: a structure with a bound ligand is known; it has a binding pocket of medium quality. PROTAC: ubiquitination databases record sites on it; its protein half-life has been measured.
Gene: Protein-coding gene on chromosome 1 (100,182,222 to 100,249,873, reverse strand). Ensembl gene ENSG00000137992.
Subcellular location: Mitochondrion matrix
Subcellular location (Human Protein Atlas): Mitochondria
Pathways (Reactome):
Disease: Branched-chain ketoacid dehydrogenase kinase deficiency; H139Hfs13* PPM1K causes a mild variant of MSUD; Loss-of-function mutations in BCKDHA or BCKDHB cause MSUD; Loss-of-function mutations in DBT cause MSUD2; Loss-of-function mutations in DLD cause MSUD3/DLDD
Metabolism: BCKDH synthesizes BCAA-CoA from KIC, KMVA, KIV; Branched-chain amino acid catabolism
Metabolism of proteins: Mitochondrial protein degradation; Protein lipoylation
Signal Transduction: RHOH GTPase cycle
Gene Ontology:
Molecular function: protein binding; ubiquitin protein ligase binding; acyltransferase activity, transferring groups other than amino-acyl groups; dihydrolipoamide branched chain acyltransferase activity; acyltransferase activity
Biological process: branched-chain alpha-keto acid decarboxylation to branched-chain acyl-CoA; branched-chain amino acid catabolic process; L-isoleucine catabolic process; L-leucine catabolic process; L-valine catabolic process
Cellular component: branched-chain alpha-ketoacid dehydrogenase complex; mitochondrial nucleoid; mitochondrion; mitochondrial matrix
Genetic constraint (gnomAD): Loss-of-function variants: 27 observed, 29.67 expected, observed/expected ratio (o/e) 0.91, 90% interval 0.67 to 1.25. The upper end of that interval is the gene's LOEUF score, 1.25, which puts it in group 5 of 6, group 1 being the genes least tolerant of losing a copy. Missense variants: 359 observed, 434.57 expected, observed/expected ratio (o/e) 0.83, 90% interval 0.76 to 0.9. Synonymous variants: 133 observed, 143.05 expected, observed/expected ratio (o/e) 0.93, 90% interval 0.81 to 1.07.
Gene-disease validity (ClinGen):
ClinGen rates the evidence that DBT causes each of these diseases.
maple syrup urine disease (autosomal recessive): Definitive. An autosomal recessive inherited disorder caused by mutations in the BCKDHA, BCKDHB, DBT, and DLD genes.
Homologues: Orthologues: macaque DBT (98% identical), chimpanzee DBT (96% identical), dog DBT (91% identical), pig DBT (89% identical), guinea pig DBT (88% identical), mouse Dbt (88% identical), rat Dbt (88% identical), tropical clawed frog dbt (76% identical), zebrafish dbt (71% identical), Caenorhabditis elegans dbt-1 (51% identical), Drosophila melanogaster Dbct (48% identical). Paralogues in human: DLAT (26% identical), DLST (23% identical), PDHX (23% identical).
Diseases named in the same sentence as DBT in open-access papers:
DBT is named in the same sentence as 42 diseases in open-access papers, as found by Europe PMC text mining. Sharing a sentence is not in itself a finding about the gene and the disease. The quoted sentences say what the papers report.
maple syrup urine disease (17 papers, 2013 to 2025). "Maple syrup urine disease is another metabolic disorder, caused by mutations in the dihydrolipoamide branched-chain transacylase E2 (DBT) gene, which can result in severe dystonia." (PMID 29910763, 2018). "Maple syrup urine disease is associated with mutation in DBT, BCKDHB, and BCKDHA genes." (PMID 25029527, 2014). "Pathogenic biallelic variants in the BCKDHA, BCKDHB, or DBT genes are responsible for the inborn error of metabolism known as Maple Syrup Urine Disease (MSUD)." (PMID 40710547, 2025). "In addition, mutations in the DBT gene can occur, and such mutations can cause maple syrup urine disease (MSUD) and may have serious consequences, such as dystonia or even death." (PMID 36299888, 2022). "Maple syrup urine disease (MSUD) is a rare autosomal recessive metabolic disorder caused by variants in any of the following genes: BCKDHA, BCKDHB, and DBT gene." (PMID 39456016, 2024). "Maple syrup urine disease (MSUD) is an autosomal recessive genetic disorder that originates from mutations in genes for the BCKDH complex, such as BCKDHA/B, DBT, and DLD44." (PMID 38956299, 2024). "Maple syrup urine disease (MSUD) is an autosomal recessive inherited metabolic disorder caused by mutations in the BCKDHA, BCKDHB, DBT, and DLD genes." (PMID 29740478, 2018). "Maple syrup urine disease (MSUD) is an autosomal recessive metabolic disorder originating from defects in the branched-chain α-ketoacid dehydrogenase (BCKDH) complex encoded by BCKDHA, BCKDHB and DBT." (PMID 38837343, 2024). "Maple syrup urine disease (MSUD) is an autosomal recessive disorder of branched chain amino acid (leucine, valine, isoleucine) catabolism due to branched-chain alpha-ketoacid dehydrogenase complex (BCKD) deficiency encoded by BCKDHA, BCKDHB, and DBT genes." (PMID 32752260, 2020). "For example, among the 19 diseases with ‘Ketosis’ as clinical sign, two of them were classified as oligogenic: maple syrup urine disease with 3 genes (BCKDHA, BCKDHB and DBT) and Permanent neonatal diabetes mellitus with 4 genes (GCK, INS, KCNJ11 and ABCC8)." (PMID 28715999, 2017). "Sequence analysis of the three maple syrup urine disease (MSUD) genes, BCKDHA, BCKDHB, or DBT, in two unrelated cases of known biochemical diagnosis of MSUD detected only one familial mutation each." (PMID 24304607, 2013).
clear cell renal cell carcinoma (6 papers, 2022 to 2025). "Overexpression of dihydrolipoamide branched chain transacylase E2 (DBT), which encodes one of the three subunits of BCKD complex, inhibits the invasiveness of renal clear cell carcinoma (KIRC)." (PMID 40367233, 2025). "This study aims to determine the significance of dihydrolipoamide branched chain transacylase E2 (DBT) in patients with Sunitinib-Resistant Clear-Cell Renal Cell Carcinoma (RCC)." (PMID 38305803, 2024). "DBT has been characterized as a tumor suppressor that inhibits tumor progression and corrects lipid metabolism disorders through the DBT/ANXA2/YAP axis-regulated Hippo signaling pathway in clear cell renal cell carcinoma." (PMID 38722401, 2024). "The current study found for the first time that both the mRNA expression and protein expression of DBT were downregulated in ccRCC, and were also verified in many renal cancer cell lines and in renal clear cell carcinoma tissues from our study centre." (PMID 36299888, 2022). "The results demonstrated that ATP7B, DLAT, and LIAS were upregulated in the 786-O cell line, which represented human renal clear cell adenocarcinoma cell, compared to the HK-2 cell line; while DBT and PDHB were found to be downregulated in 786-O cells." (PMID 36092880, 2022). "In clear cell renal cell carcinoma (ccRCC), METTL3-m6A modification reduces dihydrolipoamide branched chain transacylase E2 (DBT) expression and promotes tumor progression and corrects the lipid metabolism disorder." (PMID 40428320, 2025).
breast carcinoma (3 papers, 2022 to 2023). "Additionally, it was discovered via research of the impact of gene expression patterns on overall survival in breast cancer that those expressing high levels of ATP7A, DBT, DLAT, DLD, GLS, PDHA1, and SLC31A1 had a bad prognosis." (PMID 36059516, 2022).
pancreatic cancer (3 papers, 2023 to 2025). "Following that, we identified DBT-associated DEGs using bioinformatics analysis and discovered that DBT regulates a number of cancer-related signaling pathways, including the PPAR signaling route, TGF signaling pathway, KEGG-pancreatic cancer, KEGG-prostate cancer, and KEGG-renal cell carcinoma." (PMID 37383233, 2023).
celiac disease (2 papers, 2022 to 2024). An autoimmune genetic disorder with an unknown pattern of inheritance that primarily affects the digestive tract. "Cuproptosis-related regulators exhibited extensive differential expression in Crohn’s Disease (CD), Ulcerative Colitis (UC), Celiac Disease (CEL), and IBD-induced cancer (IBD-CA) that share common differential genes (PDHA1, DBT, DLAT, LIAS)." (PMID 36405733, 2022).
cervical cancer (2 papers, 2023 to 2024). A primary or metastatic malignant neoplasm involving the cervix. "Dihydrolipoamide Branched Chain Transacylase E2(DBT) catalyzed α-keto acid to acyl-CoA, which is thought to be associated with protective effects in both LUAD and cervical cancer(CC) patients." (PMID 36882769, 2023). "Dihydrolipoamide Branched Chain Transacylase E2 (DBT), a key enzyme in transforming α-keto acid into acyl-CoA, served as a protective factor in cervical cancer." (PMID 38797784, 2024).
MSUD type 2 (2 papers, 2023 to 2025). "additionally, biallelic pathogenic variants in DBT encoding the dihydrolipoyl transacylase (E2) subunit is also called MSUD type 2." (PMID 39773751, 2025). "Dihydrolipoamide branched chain transacylase E2 (DBT) encodes one of the three subunits of BCKD, and mutations in this gene cause type 2 maple syrup urine disease." (PMID 37383233, 2023).
periodontitis (2 papers, 2023 to 2025). An acute or chronic inflammatory process that affects the tissues that surround and support the teeth. "In our study, DBT expression was downregulated in the livers of periodontitis-induced rats, potentially offering new mechanistic insights and therapeutic targets." (PMID 40951429, 2025). "Furthermore, the downregulation of DBT, ACOX1, ACAA2, and HADHA in the liver provides valuable insights for developing therapeutic strategies for periodontitis-associated NAFLD." (PMID 40951429, 2025). "Based on these findings, DBT, ACOX1, ACAA2 and HADHA emerge as potential key targets linking periodontitis to NAFLD." (PMID 40951429, 2025).
renal cell carcinoma (2 papers, 2023 to 2024). "In our comprehensive study involving patients with renal cell carcinoma (RCC), we conducted an in-depth assessment of the roles played by dihydrolipoamide branched chain transacylase E2 (DBT) and genes associated with cuproptosis." (PMID 38305803, 2024). "To delve deeper into the biological functions of DBT in kidney cancer, specifically in kidney renal clear cell carcinoma (KRCC), we conducted a detailed examination of DBT's mRNA and protein levels in two renal cell carcinoma (RCC) cell lines: 786-O and A498." (PMID 38305803, 2024).
amyotrophic lateral sclerosis (1 paper, 2024). Amyotrophic lateral sclerosis (ALS) is a neurodegenerative disease characterized by progressive muscular paralysis reflecting degeneration of motor neurons in the primary motor cortex, corticospinal tracts, brainstem and spinal cord. "Dihydrolipoamide branched chain transacylase E2 (DBT) is abnormally upregulated in amyotrophic lateral sclerosis (ALS) patient neurons." (PMID 39255192, 2024).
colorectal cancer (1 paper, 2025). A primary or metastatic malignant neoplasm that affects the colon or rectum. "DBT (dihydrolipoamide branched-chain transacylase E2) encodes an essential component of the branched-chain α-ketoacid dehydrogenase complex, and its low expression in colorectal cancer inhibits the cuproptosis process." (PMID 40276654, 2025). "The study revealed that, compared to normal tissues, genes FDX1, DLD, DBT, DLST, and DLAT were significantly downregulated in colorectal cancer tissues, while LIPT1, GCSH, and ATP7B genes were upregulated." (PMID 40276654, 2025).
Hyperleucinemia (1 paper, 2022). An increased concentration of leucine in the blood. "For example, in a 3-month-old male index with seizures, body odor, hyperisoleucinemia, hyperleucinemia, and hypervalinemia, we identified a heterozygous likely pathogenic frameshift variant and a heterozygous likely pathogenic deletion of exons 2-3 of the DBT gene." (PMID 35614200, 2022).
liver cancer (1 paper, 2023). An epithelial or non-epithelial malignant neoplasm that arises from the liver. "Moreover, we used the Kaplan–Meier plotter tool to analyze the overall survival of patients with liver cancer based on the expression of the FDX1, DBT, GCSH, SLC31A1, and DLAT genes." (PMID 37763758, 2023).
nephritis (1 paper, 2008). Inflammation of renal tissue. "Transcripts for BCKDHA and DBT, two enzymes in the branched chain amino acid metabolism pathway required for the catabolism of leucine, valine and isoleucine, are reduced in nephritis, perhaps leading to the accumulation of leucine in diseased tissue." (PMID 18980674, 2008).
ovarian carcinoma (1 paper, 2022). A malignant neoplasm originating from the surface ovarian epithelium. "Among CNV increasing genes, only DLD in ovarian cancer samples was higher than that in normal ovarian tissues, while the expression levels of DBT, PDHB, ATP7B, etc. with CNV deletion were not consistent with CNV changes." (PMID 36307842, 2022).
Parkinson disease (1 paper, 2022). A progressive degenerative disorder of the central nervous system characterized by loss of dopamine producing neurons in the substantia nigra and the presence of Lewy bodies in the substantia nigra and locus coeruleus. "Our results identified three characteristic cuprotosis-related genes ATP7A, SLC31A1, and DBT involved in the immune process of Parkinson’s disease." (PMID 36338988, 2022).
viral myocarditis (1 paper, 2024). Myocarditis that is caused by an infection with a viral agent. "Overexpression of DBT and SLC31A1 is involved in Leishmania infection, glycan biosynthesis, and viral myocarditis." (PMID 39315155, 2024).
tumor (20 papers, 2008 to 2025). "Concurrently, dihydrolipoamide branched chain transacylase E2 (DBT) functions as a tumor suppressor by inhibiting tumor progression and rectifying lipid metabolism abnormalities in ccRCC." (PMID 40313614, 2025). "Compared with normal mouse liver tissues, the expression of BCAT2 was higher, while the expressions of BCKDHA and DBT were lower in the tumor tissues of DEN and CCl4-induced HCC mouse models." (PMID 38580754, 2024). "Here, we explored the expression and prognostic significance of DBT in ccRCC and identified DBT as a tumour suppressor gene." (PMID 36299888, 2022). "qRT−PCR results on CCA samples showed that FDX1, DBT were significantly downregulated in tumor tissue samples, while ATP7A was significantly upregulated." (PMID 36568224, 2022). "Moreover, we uncovered DBT's role in the tumor immune environment, suggesting that DBT may contribute to cancer development by initiating abnormal inflammatory and immune reactions." (PMID 38305803, 2024). "Specifically, genes such as LIPT1, ATP7A, LIAS, DBT, and PDHB were found to be significantly downregulated in the tumor tissue." (PMID 38898987, 2024). "Cu transporter-related genes including ATP7A, SLC31A1, and TCA-related genes including DBT, DLST, and DLAT are differentially expressed between normal and tumor samples." (PMID 36438201, 2022). "A heatmap showed that the levels of expression of ATP7B, DLAT, DLD, LIAS, and SLC31A1 were upregulated and the levels of expression of DBT, FDX1, and PDHB downregulated in tumor samples." (PMID 36092880, 2022). "ATP7A expression was significantly higher in tumor tissues than in paraneoplastic tissues, while FDX1, DBT, and LIAS expression was significantly lower than in paraneoplastic tissues (P<0.05)." (PMID 36568224, 2022). "Levels of expression of the ATP7B, DLAT, and LIAS proteins were higher, whereas the levels of expression of DBT and PDHB were lower, in tumor samples than in non-tumorous kidney tissue, in accordance with the results of differential mRNA analysis." (PMID 36092880, 2022).
cancer (10 papers, 2017 to 2024). A tumor composed of atypical neoplastic, often pleomorphic cells that invade other tissues. "Understanding these interactions and pathways is crucial for comprehending the role of DBT in normal cellular function and its potential implications in diseases, including cancer." (PMID 38305803, 2024). "While direct studies connecting DBT and DLAT mutations to cancer are scarce, the significant role these enzymes play in metabolic pathways suggests they could impact LUAD development and progression by causing metabolic dysregulation." (PMID 38722401, 2024). "DBT is also the E2 subunit of the pyruvate dehydrogenase complex (PDC), which is mainly involved in the TCA cycle and glycolytic pathways and has been shown by studies to be closely associated with the development and progression of cancer." (PMID 36299888, 2022). "Interestingly, in our study, correlation analysis revealed a negative correlation between immune cell infiltration and the expression levels of DLAT and DBT, suggesting that cuproptosis-related genes such as DLAT and DBT may promote the invasion of cancer cells through immunosuppression." (PMID 38722401, 2024). "Prior research has indicated that in various human cancers, the expression of DBT (dihydrolipoamide branched chain transacylase E2) is often reduced." (PMID 38305803, 2024). "In total, 14 DECRs were identified, of which six regulators (MTF1, DLST, NLRP3, DBT, FDX1, and DLD) were downregulated in cancer tissues." (PMID 36672336, 2023). "The transcriptional levels of DLAT, FDX1, DBT, DLD, PDHB, and GCSH negatively correlate with methylation in part of tumors (> 7 cancer types)." (PMID 36209249, 2022).
digestive diseases (1 paper, 2022). "The four overlapping genes, including LIAS, DLAT, DBT, and PDHA1, were dysregulated expressed in the interaction between the four digestive diseases using the Venn diagram." (PMID 36405733, 2022).
neurodegenerative disease (1 paper, 2024). A disorder of the central nervous system characterized by gradual and progressive loss of neural tissue and neurologic function. "The observations of DBT’s robust regulatory effects on the proteotoxicity in models of neurodegenerative diseases and the upregulation of DBT in ALS patient tissues suggest that DBT is an important player in the pathogenesis of the disease." (PMID 39255192, 2024).
DBT also shares sentences with these, for which no sentence is quoted: metabolic disorder (5 papers); infection (3); Crohn disease (2); ulcerative colitis (2); biotinidase deficiency (1); Dystonia (1); ependymoma (1); Hartnup disease (1); hematological diseases (1); Hypervalinemia (1); kidney cancer (1); lipid metabolism disorder (1); Meckel -Gruber Syndrome (1); melanoma (1); Methylmalonic aciduria (1); neonatal diabetes mellitus (1); osteomyelitis (1); pontocerebellar hypoplasia type 6 (1); prostate carcinoma (1); renal carcinoma (1); type I citrullinemia (1).